XPNPEP2 (X-prolyl aminopeptidase 2)
Description:
Membrane-bound metalloprotease which catalyzes the removal of a penultimate prolyl residue from the N-termini of peptides, such as Arg-Pro-Pro. May play a role in the metabolism of the vasodilator bradykinin.
Synonyms: AEACEI; APP2
Tractability: Small molecule: a drug acting on it is in phase 2 or 3 trials; it belongs to a druggable protein family. Antibody: its Gene Ontology location is reachable by antibodies, with high confidence; UniProt places it where antibodies can reach, with medium confidence; UniProt predicts a signal peptide or a membrane-spanning region; the Human Protein Atlas places it where antibodies can reach. PROTAC: its protein half-life has been measured; a small molecule that binds it is known.
Target class: Metallo protease MG clan; Metallo protease M24B subfamily; Enzyme; Protease; Metallo protease
Safety:
Unwanted effects reported when the protein is acted on. In parentheses: how it was acted on, where the effect was seen, and who reports it.
angioedema (source: ClinPGx)
Gene: Protein-coding gene on chromosome X (129,738,949 to 129,769,547, forward strand). Ensembl gene ENSG00000122121.
Subcellular location: Cell membrane
Subcellular location (Human Protein Atlas): Cytosol; Plasma membrane
Pathways (Reactome):
Metabolism of proteins: Post-translational modification: synthesis of GPI-anchored proteins
Gene Ontology:
Molecular function: aminopeptidase activity; metalloaminopeptidase activity
Cellular component: extracellular exosome; extracellular region; membrane; plasma membrane
Homologues: Orthologues: macaque XPNPEP2 (98% identical), chimpanzee XPNPEP2 (91% identical), pig XPNPEP2 (85% identical), dog XPNPEP2 (84% identical), rat Xpnpep2 (81% identical), mouse Xpnpep2 (81% identical), rabbit XPNPEP2 (79% identical), guinea pig XPNPEP2 (72% identical), tropical clawed frog xpnpep2 (60% identical), zebrafish xpnpep2 (56% identical), Caenorhabditis elegans app-1 (32% identical), Caenorhabditis elegans pid-5 (27% identical), and 2 more. Paralogues in human: XPNPEP1 (39% identical), XPNPEP3 (15% identical), PEPD (13% identical), METAP2 (11% identical), METAP1D (9% identical), METAP1 (9% identical), PA2G4 (8% identical).
Diseases named in the same sentence as XPNPEP2 in open-access papers:
XPNPEP2 is named in the same sentence as 27 diseases in open-access papers, as found by Europe PMC text mining. Sharing a sentence is not in itself a finding about the gene and the disease. The quoted sentences say what the papers report.
cervical cancer (6 papers, 2019 to 2025). A primary or metastatic malignant neoplasm involving the cervix. "Decreased expression and activity of XPNPEP2 have been reported in hypertensive patients, whereas overexpression of XPNPEP2 has been reported in patients with cervical cancer and clear-cell renal cell carcinoma." (PMID 41573684, 2025). "To further determine the expression of XPNPEP2 in cervical cancer, we added 45 cervical cancer specimens in this study." (PMID 31695771, 2019). "Additionally, Cheng te.al revealed that XPNPEP2 facilitated cervical cancer cell invasion and migration by inducing epithelial-mesenchymal transition." (PMID 31296901, 2019). "Our previous study has suggested that XPNPEP2, the potential receptor of TMTP1, can serve as a potential biomarker in metastatic cervical cancer." (PMID 31695771, 2019). "It is known that XPNPEP2 is overexpressed in cervical cancer, promoting cell invasion and migration without affecting cell proliferation and apoptosis." (PMID 33470396, 2021).
angioedema (4 papers, 2010 to 2021). Swelling involving the deep dermis, subcutaneous, or submucosal tissues, representing localized edema. "Genetic variants in the gene encoding APP (XPNPEP2), resulting in reduced enzyme activity, higher bradykinin and des-Arg9-BK have been associated with angioedema induced by ACE inhibitors." (PMID 20667119, 2010). "XPNPEP2 (OMIM: 300145) has been implicated in ACE inhibitor-induced angioedema." (PMID 24784881, 2014). "The XPNPEP2 gene codes for APP, and it has been shown that a variant of this gene was more prevalent in cases of ACEi angioedema compared to controls." (PMID 34449608, 2021). "Several studies have demonstrated the correlation between polymorphisms and haplotype mutations of XPNPEP2 and ACEI-induced angioedema." (PMID 31296901, 2019).
lymph node metastasis (3 papers, 2019 to 2022). "In summary, we demonstrated that serum XPNPEP2 level was associated with lymph node metastasis and local invasion." (PMID 31296901, 2019). "Bioinformatic methods also verified that serum XPNPEP2 could be a potential biomarker for lymph node metastasis." (PMID 31296901, 2019). "Our study demonstrated that level of serum XPNPEP2 had correlation with lymph node metastasis." (PMID 31296901, 2019). "In terms of lymph node metastasis, differential expression of NEGR1, NTNG1, XPNPEP2, CD109, OPCML, and PRND had statistical significance in the groups of N0 and N1." (PMID 34737762, 2021).
COVID-19 (2 papers, 2024 to 2025). A disease caused by infection with severe acute respiratory syndrome coronavirus 2. "The following proteins have sparked interest in COVID-19 patients: XPNPEP2, HCII, ORP150, CREB3L3, APOA1, and CUBN." (PMID 38510452, 2024). "Studies have demonstrated elevated expression levels of XPNPEP2 in the lungs of COVID-19 patients compared to healthy individuals, which is consistent with the actively researched concept of a “cytokine storm”." (PMID 38510452, 2024). "Furthermore, an upregulation of XPNPEP2 expression in the lungs of COVID-19 patients, aligning with the “cytokine storm” hypothesis, has been documented." (PMID 40160464, 2025).
Hypertension (1 paper, 2025). The presence of chronic increased pressure in the systemic arterial system. "These vascular phenotypes in mice are consistent with hypertension-related microvascular structural remodeling and dysfunction, suggesting that the effects of XPNPEP2 on EC function and angiogenesis could explain some of the etiology of cardiovascular diseases caused by XPNPEP2 defects." (PMID 41573684, 2025).
hypertensive nephropathy (1 paper, 2025). Kidney damage that results from chronically elevated blood pressure; complications include glomerular damage resulting in proteinuria and hematuria. "The public database of Gene Expression Omnibus (GEO) profiles revealed that lower levels of XPNPEP2 are present in failing heart or hypertensive mouse artery, hypertensive nephropathy, and anti-angiogenesis models, indicating its potential role in EC function." (PMID 41573684, 2025).
metastatic prostate carcinoma (1 paper, 2019). A carcinoma that arises from the prostate gland and has spread to other anatomic sites. "In addition, we analyzed XPNPEP2 gene alterations using data extracted from the cBioPortal online analysis tool and found that metastatic prostate cancer has the highest frequency of XPNPEP2 gene amplification." (PMID 31296901, 2019).
Pca (1 paper, 2019). "For the evaluation of the associations between protein expression and clinicopathologic datas, XPNPEP2 expression in patients with localized, locally invasive and LN-metastatic Pca were analyzed, respectively." (PMID 31296901, 2019). "For primary evaluation of XPNPEP2 expression in Pca patients, a prostate cancer tissue microarray and other BPH tissue samples obtained from Tongji hospital were utilized." (PMID 31296901, 2019). "XPNPEP2 expression was lower in prostate samples from Pca patients including localized and lymph node metastasis than normal or BPH patients." (PMID 31296901, 2019). "In summary, serum XPNPEP2 levels when combined with PSA levels may result in increased sensitivity for predicting LN metastasis in Pca patients, especially for patients with low serum PSA levels." (PMID 31296901, 2019). "In general, XPNPEP2 expression was lower in prostate cancer tissue than in normal prostate tissue, but was higher in prostate cancer tissues with local invasion and LN metastasis than in tissues with localized Pca." (PMID 31296901, 2019). "Therefore, combined application of serum XPNPEP2 levels and PSA levels might improve diagnostic accuracy of Pca patients with LN metastasis." (PMID 31296901, 2019). "However, there was a discrepancy between the plasma and tissue levels of XPNPEP2 in Pca patients." (PMID 31296901, 2019). "Especially for Pca patients with low serum PSA levels, XPNPEP2 was a powerful marker for predicting LN metastasis." (PMID 31296901, 2019). "The mRNA levels of XPNPEP2 were also reduced in PCa by GEPIA analysis." (PMID 31296901, 2019).
prostate carcinoma (1 paper, 2019). A carcinoma that arises from epithelial cells of the prostate gland. "The results showed that XPNPEP2 was moderately expressed in the normal prostate tissues, but significantly decreased in the prostate cancer." (PMID 31296901, 2019). "Interestingly, among these 36 examined cancer types or subtypes, prostate cancer had the highest frequency of XPNPEP2 gene amplifications." (PMID 31296901, 2019). "Hence we used TCGA, IHC, and ELISA to further analyze the expression of XPNPEP2 in tissues and serum of prostate cancer patients." (PMID 31296901, 2019). "We confirmed that the expression of XPNPEP2 was significantly lower in prostate cancer tissues than normal prostate tissues." (PMID 31296901, 2019).
prostate hyperplasia (1 paper, 2019). "However, there was little information about the physiological roles and clinical significance of XPNPEP2 in prostate diseases." (PMID 31296901, 2019).
tumor (8 papers, 2019 to 2025). "Concordant results showed that the loss of XPNPEP2 leads to delayed wound healing and slow tumor growth due to abnormal vascularization, supporting that XPNPEP2 is involved in angiogenesis with high ATP demand." (PMID 41573684, 2025). "XPNPEP2 is a proline hydrolytic enzyme that hydrolyzes peptides to cause a loss of substrate activity and finally helps tumor metastasis in the microenvironment." (PMID 32385351, 2020). "Immunofluorescence experiments showed that ITM mostly co-localized with XPNPEP2 and further demonstrated the plausibility of targeting tumor cells by TMTP1." (PMID 31695771, 2019). "In vivo, XPNPEP2 deletion led to pathological changes in the pulmonary artery wall and renal tissue, decreased venous blood vessel density in the proximal region of superficial retinal vessels, and significantly slowed wound healing and tumor growth in mice." (PMID 41573684, 2025). "It was supposed that ITM could arrive in the tumor via interaction with XPNPEP2 expressed on the tumor cells." (PMID 31695771, 2019). "Finally, confocal imaging of SLNs confirmed the high accumulation of ITM in the metastatic SLN compared to the IM group, and ITM mostly co-localized with XPNPEP2 expression on tumor cells in metastatic SLN." (PMID 31695771, 2019). "Thus, such high availability of XPNPEP2 expression on the tumor cells facilitated ITM active targeting of tumor cells." (PMID 31695771, 2019). "Aminopeptidase P2 (XPNPEP2) is a receptor for TMTP1 tumor-homing peptide." (PMID 31296901, 2019). "Notably, the reduced expression of XPNPEP2 and XG implies heightened vascular permeability and an inflammatory microenvironment, which may further facilitate tumor progression." (PMID 40950184, 2025). "When the same analyses were done using PEA Oncology II profiling data, 10 proteins correlated to tumor stage (P < 0.05), for example, CD160, TNFRSF4/OX40L, XPNPEP2, SPARC, MAD homolog 5/SMAD5, CPE, hK8/KLK8, WIF‐1, TCL1A, and MIC‐A/B." (PMID 33768639, 2021). "In terms of tumor stage, differential expression of NEGR1, NTNG1, XPNPEP2, CD109, and PRND had statistical significance in all tumor stage groups." (PMID 34737762, 2021). "The other TSGs, such as SEPP1, TMEM25, XPNPEP2, and G6PC, have been reported to play a role in tumor suppression." (PMID 32774369, 2020).
cancer (4 papers, 2019 to 2021). A tumor composed of atypical neoplastic, often pleomorphic cells that invade other tissues. "Cross-cancer XPNPEP2 alteration analysis demonstrated that XPNPEP2 is frequently altered in different types of cancers." (PMID 31296901, 2019). "Although it is known that this aminopeptidase activates growth factors, hormones, coagulants, toxins, cytokines, and neurotransmitters, the role of XPNPEP2 in cancer is still unknown." (PMID 33470396, 2021). "CBFA2T3 and XPNPEP2 were downregulated in 15 and 10 TCGA cancer types." (PMID 32774369, 2020). "However, researches that reveal the role of XPNPEP2 in cancer are insufficient." (PMID 31296901, 2019). "In order to explore only genes related to cancer, we selected four genes, including three that were upregulated via copy number gain (ANOS1, ETV1, and XPNPEP2) and one gene (PCDH11Y) that was downregulated via copy number loss." (PMID 33470396, 2021). "It is worth noting that the expression of APOA4, GCG, CYP3A4, XPNPEP2, and FOXP3, JUN were different between cancer and normal samples in TCGA database." (PMID 32547867, 2020). "In Hp+-AG-IM network the expression of APOA4, GCG, CYP3A4, XPNPEP2 and FOXP3, JUN were statistically different in the comparison of normal and cancer in TCGA database." (PMID 32547867, 2020).
cardiovascular disease (1 paper, 2025). "X-prolyl aminopeptidase 2 (XPNPEP2), which is abundantly expressed in vascular endothelial cells (ECs), has been reported to be associated with cardiovascular disease and angiogenesis." (PMID 41573684, 2025).
XPNPEP2 also shares sentences with these, for which no sentence is quoted: infection (9 papers); bacterial infection (2); atherosclerosis (1); bacteremia (1); clear-cell renal cell carcinoma (1); endotoxemia (1); ischemia (1); lung carcinoma (1); ovarian failure (1); Pleuritis (1); pneumonia (1); Pseudomonas infection (1); thyroid cancer (1); vitamin B12 deficiency (1).